SPI1 (Spi-1 proto-oncogene)
Diseases named in the same sentence as SPI1 in open-access papers (continued):
Sharing a sentence is not in itself a finding about the gene and the disease.
Salmonella Infections (47 papers, 2008 to 2025). Infections with bacteria of the genus SALMONELLA. "The SPI-1-encoded proteins are also required for the complex immune responses of host cells during Salmonella infection." (PMID 31428589, 2019). "These genes are normally activated during Salmonella infection of a host as a result of a regulatory cascade involving a relay of multiple activator proteins including SPI-1-encoded HilA, HilC, HilD and InvF." (PMID 31589608, 2019). "We hypothesized that differences in susceptibility to SPI-1 effectors and Salmonella host cell invasion also regulate risk of Salmonella infection." (PMID 34242364, 2021). "c2-HDA is capable of inhibiting SPI1-encoded invasion gene expression at very low concentration and may thus be further investigated as an inhibitor of Salmonella infection." (PMID 32690633, 2020). "The vast majority (approx. 75%) of the overlapping virulence genes encode key determinants of the SPI-1 (Salmonella Pathogenicity Island 1) and SPI-2 Type III Secretion Systems (T3SS-1 and T3SS-2), which play crucial roles in Salmonella infection." (PMID 39201506, 2024). "The various SPI-1 effector proteins identified in Salmonella have different roles during Salmonella infection, such as alteration of host cytoskeleton, cell metabolism and regulation of host inflammatory response." (PMID 37771590, 2023). "SPI-1 is involved in the entire Salmonella infection process, including invasion, macrophage proliferation, and host responses." (PMID 35722296, 2022). "Together these data differentiate KDM6B activation from its demethylase activity in the context of Salmonella infection, and reveal requirement of SPI1 effector(s) in this process." (PMID 34696686, 2021). "The hilA gene, a member of the transcriptional regulator genes encoded in the Salmonella pathogenicity island 1 (SPI1), plays an important role in the pathogenesis of Salmonella infection by activating the expression of SPI1." (PMID 34638177, 2021). "The SPI-1 T3SS is crucial for Salmonella infection, but other systems, including flagella and fimbrial operons, contribute to Salmonella pathogenesis." (PMID 32545652, 2020). "SopB is an important SPI-1 secreted virulence effector and exerts many roles during Salmonella infection." (PMID 31024858, 2019). "Although SPI-1 is therefore crucial for Salmonella infection, it has a retarding effect on the growth rate, presumably as a consequence of the energetically high costs to produce the SPI-1 T3SS." (PMID 29879120, 2018). "Salmonella infection occurs mainly by expression of two Salmonella pathogenicity Islands (SPI-1 and SPI-2)." (PMID 25566242, 2014). "Invasion of intestinal epithelial cells is a critical step in Salmonella infection and requires the expression of genes located in Salmonella pathogenicity island 1 (SPI-1)." (PMID 22291968, 2012). "More generally, Salmonella infection is a sequential process, initiated by Salmonella inducing its own uptake into host cells via the effects of SPI-1 effector proteins, and followed by intracellular manipulation of host cell functions by the SPI-2 T3SS." (PMID 21390246, 2011). "For example, the expression of some genes coding for SPI-1 proteins, including SopA, has been shown to be induced upon invasion of both macrophages and epithelial cells and at the late stage of Salmonella infection in animals." (PMID 21949647, 2011). "The previously unrecognized strain heterogeneity in SPI-1 expression and invasiveness has important implications for studies of Salmonella infection." (PMID 21493681, 2011). "Studies utilizing these more complex model systems demonstrated that SPI-1 was critical in the establishment of a Salmonella infection." (PMID 21206750, 2010). "Chracterization of the expression patterns of the genes of SPI-1 and other SPIs should provide insight into the functional roles of these factors in Salmonella infection." (PMID 19371445, 2009).
Salmonella Infections (continued). "Taken together, these results indicate that AvrA can specifically influence the transcriptional output stimulated by effectors of its SPI-1 TTSS during Salmonella infection." (PMID 19779561, 2009). "Furthermore, SPI-1 affects the whole process of Salmonella infection, including pathogen invasion, proliferation, and host responses, while SPI-2 confers the ability of Salmonella to survive in human macrophages." (PMID 38558876, 2024). "Human macrophages undergo SPI-1 T3SS-dependent inflammasome activation during Salmonella infection." (PMID 35073381, 2022). "In addition to enabling Salmonella invasion, interactions between the SPI-1 secreted effectors and host machinery drive inflammation that is characteristic of Salmonella infections (Reviewed)." (PMID 34242364, 2021). "SPI1 is one of the key virulence factors for Salmonella infection and invasion." (PMID 34638177, 2021). "SPI-1/-2 encodes a type three secretion system (T3SS), which is important for the injection of effector proteins into the host cells for modulation of the course of Salmonella infection." (PMID 34497590, 2021). "Greater insights into SPI-1 and its complex regulatory network might contribute to drug investigation and Salmonella infection control." (PMID 31428589, 2019). "We also demonstrated that BCA could inhibit the polarization to M2 MΦ induced by Salmonella infection by down-regulation of SPI-1 genes expression." (PMID 30271755, 2018). "The identification of SPI-1, shared by all Salmonella species and subspecies, as critical for bacterial mediated endocytosis into epithelial cells initiated decades of research into the role of horizontally acquired genes in Salmonella infections." (PMID 29034217, 2017). "The temporal coordination of flagellar and Spi-1 gene expression plays an important role during the initial phase of the Salmonella infection cycle when the bacteria are initially motile in the lumen and subsequently turn on Spi-1 virulence genes needed for invasion of the epithelial layer." (PMID 26441883, 2015). "Results from these studies and the naturally occurring Salmonella infection, demonstrate the lack of dependence of Salmonella on SPI-1 to cause disease in human and animal hosts." (PMID 21206750, 2010). "Furthermore, these data strongly suggest that different SPI-1 factors are specifically expressed at late stage of Salmonella infection, and highlight a possible role of SipC in late phase of macrophage and in vivo infections of Salmonella." (PMID 20529336, 2010). "Similarly, at 7 days post Salmonella infection, flies infected with wild type have begun to die, while those infected with a SPI1,SPI2 mutant strain will live for several more days despite carrying dramatically higher loads of bacteria." (PMID 18654628, 2008). "Additionally, our findings showed that BCA downregulated SPI-1 (Salmonella pathogenicity island 1) expression during Salmonella infection in vitro and in vivo to reverse the MΦ M2 polarization, which was different from the MΦ M1 phenotype caused by most of bacteria infection." (PMID 30271755, 2018). "Thus, detection of specific environmental cues could be required for the repression of SPI-1 by SsrB in physiological conditions, which could occur during Salmonella infection of hosts." (PMID 28704543, 2017). "Therefore, these genes could be expected to be induced at an early stage, as they are key modulators of invasive Salmonella infection and hilD appears to bridge communication between SPI-1 and SPI-2 regulation." (PMID 23442379, 2013). "The effects of SPI-1 and SPI-2 on activation of inflammatory pathways were evaluated in murine macrophages following Salmonella infection." (PMID 37325511, 2023). "We demonstrate that upon Salmonella infection KDM6B upregulation is followed by a concomitant decrease in overall H3K27me3 mark of host, which required Salmonella SPI1 effectors." (PMID 34696686, 2021).
Salmonella Infections (continued). "We observed NLRP3 activation induced by Salmonella infection that is likely due to activity of the SPI-1 T3SS, since we do not observe inflammasome activation when we infect THP-1 macrophages with ΔsipB." (PMID 35073381, 2022). "HilA regulates the transcriptional expression of most SPI-1 genes, including those required for the synthesis of a type III secretion system (T3SS) and several effector proteins that are translocated to the host cell during Salmonella infection." (PMID 29879120, 2018). "The mRNA levels for innate/inflammatory marker genes such as SPI1 were strongly up-regulated following Salmonella infection (data not shown)." (PMID 26227241, 2015). "A detailed analysis of the kinetics of PB disassembly upon Salmonella infection revealed that PB integrity is not affected at early and intermediate times of infection (2, 4 or 8 hours p.i.) when the SPI-1 T3SS plays a major role." (PMID 21390246, 2011). "Therefore, the SPI-1 pathway, considered essential for the pathogenesis of Salmonella infection, does not explain the infection of swine cells, suggesting that an alternative mechanism is involved in this host." (PMID 33299016, 2020). "Since SPI-1 proteins are major virulence determinants essential for Salmonella invasion, we reasoned that IsrM may function to regulate the expression of SPI-1 factors, facilitating Salmonella infection and pathogenesis." (PMID 21949647, 2011). "In Salmonella, these genes are located in the Salmonella pathogenicity Islands 1 and 2 (SPI-1 and SPI-2), and they facilitate bacterial invasion and replication within macrophages, contributing to the burden of nontyphoidal Salmonella infections." (PMID 40657616, 2025).
Alzheimer disease (28 papers, 2016 to 2026). A progressive, neurodegenerative disease characterized by loss of function and death of nerve cells in several areas of the brain leading to loss of cognitive function such as memory and language. "SPI1 was recently reported as a genetic risk factor for Alzheimer’s disease (AD) in large-scale genome-wide association studies." (PMID 38734693, 2024). "The transcription factor SPI1 (PU.1) is linked to Alzheimer’s disease likely by impacting neuroinflammatory response and was found to interact with its network neighbor RUNX1 in modulating gene expression." (PMID 36344995, 2022). "Studies have shown that lower SPI1 expression can reduce the risk of Alzheimer’s disease by regulating gene expression and cellular function in myeloid lines (monocytes and macrophages)." (PMID 35237521, 2022). "Similar to this study, higher levels of expression of SPI1 is associated with increased risk for Alzheimer’s disease." (PMID 34417470, 2021). "Genetic association studies have identified multiple variants at the SPI1 locus that modify risk and age of onset for Alzheimer’s Disease (AD)." (PMID 34294785, 2021). "Moreover, human SNPs that altered SPI1 expression level were reported to be associated with Alzheimer’s disease (AD) pathogenesis." (PMID 40673490, 2025). "Although SPI1 gene was identified as a risk factor for Alzheimer’s disease, its role in the disease remains unclear." (PMID 38734693, 2024). "Together, these findings suggest that several of the predicted and established Alzheimer’s disease risk genes may be regulated by SPI1/PU.1, which itself alters Alzheimer’s disease risk by coordinating a program of microglial-expressed genes." (PMID 32274467, 2019). "Risk alleles for Alzheimer’s disease (AD) are also enriched in myeloid cells and overlapping variants for AUD and AD exist in enhancer regions of the SPI1 gene (gene that encodes for PU.1 protein)." (PMID 36157070, 2022). "LACTB2 and PLIN2 had novel significant associations with Alzheimer’s disease and BIN1, PTK2B, SPI1, MS4A4A, MS4A6E, APOE and PVR are in known Alzheimer’s disease risk loci from GWAS." (PMID 33959712, 2021). "In support of these findings, variants in the proximity of both SPI1 and MEF2C have earlier been identified as significant Alzheimer’s disease risk loci." (PMID 33568722, 2021). "ITGAM/CD11b was highlighted in recent genetic and functional analyses as likely being important for the progression of Alzheimer’s disease, whose expression was driven by SPI1/PU.1, and related to amyloid deposition in mice and humans." (PMID 32274467, 2019). "Studies have shown that increased SPI1 expression could regulate microglial immune activity and attenuate inflammation near amyloid plaques in Alzheimer’s disease, suggesting its broader role in restraining aberrant immune responses." (PMID 40979590, 2025). "For instance, SPI1, which has been identified as a candidate gene for Alzheimer’s disease via various functional genetics approaches, shows a strong activating effect with high expression of the SPI1 gene and high accessibility for the SPI1 binding motif in microglia." (PMID 37824616, 2023). "Although the neuronal role of Spi1 is unknown, its function is critical for viability of brain microglia and its alteration was reported in patients affected by Alzheimer’s disease and major psychiatric disorders." (PMID 34068160, 2021). "For example, the transcription factor PU.1 (SPI1), which regulates the expression of immune-related genes in myeloid cells, may contribute to Alzheimer’s disease by modulating essential immune pathways and influencing the epigenetic landscape." (PMID 40869138, 2025). "A decade of GWAS projects for Alzheimer’s disease has provided key and initially surprising insights into the progression of late-onset Alzheimer’s disease, particularly the dependence on the innate immune system, with the identification of genes such as TREM2 and SPI1/PU.1." (PMID 32274467, 2019).
lymphoma (27 papers, 2006 to 2026). A malignant (clonal) proliferation of B- lymphocytes or T- lymphocytes which involves the lymph nodes, bone marrow and/or extranodal sites. "ETS transcription factors, including SPIB and SPI1, are implicated in lymphoma pathogenesis and can be targeted by the small molecule TK216, which disrupts ETS-DHX9 interactions." (PMID 42130064, 2026). "MiR155 can also inhibit the transcription factor SPI1, which was within the associated region in chromosome 18 in the present study, and the upregulation of MiR-155 and downregulation of SPI1 have been observed in numerous lymphoma types." (PMID 37756103, 2023). "As revealed by GSEA, the induction of the Mφ gene signature was reduced in TIS lymphomas upon PU.1 or C/EBPβ depletion, with Spi1 knockdown also neutralizing the DC-like signature in TIS." (PMID 40159497, 2025). "To mechanistically demonstrate that lineage-aberrant TF activity drives lineage plasticity of TIS lymphomas, we depleted PU.1/SPI1, C/EBPβ and AP-1 (c-Jun) by shRNA-mediated gene knockdown." (PMID 40159497, 2025). "Spriano and colleagues previously demonstrated that TK216 disrupted SPI1/SPIB interaction with RNA helicases in lymphoma models." (PMID 37895265, 2023). "Previously, Spriano and colleagues demonstrated that TK216 disrupts the interaction between Spi1/SpiB and RNA helicases in lymphoma." (PMID 37895265, 2023). "The anti-tumor activity of TK216 is also observed in lymphoma, where it exerts its cytotoxic effects by disrupting the interaction between SpiB/Spi1 and RNA helicases, DDX5 and DHX9." (PMID 37895265, 2023). "SPI1 is required for myeloid and lymphoid lineage commitment and maturation, and its deregulation leads to development of leukaemias or lymphomas." (PMID 34841706, 2021). "In addition, PIK3CD and SPI1 were also related to different types of lymphoma." (PMID 33785011, 2021). "Analysis from three different SPI1 ChIP-seq datasets, including GSM1681425 in macrophage, GSM1703900 in B lymphocyte, and GSM1480737 in lymphoma, demonstrated that SPI1 binds to the ACAP1 promoter." (PMID 36497434, 2022). "In light of these results, we further focused on deregulated miRNAs and their putative interactions with B-cell specific transcription factors SPI1 and ELF-1 attenuated in cHL and also the NF-ĸB inhibitor TNFAIP3 recurrently inactivated in this lymphoma." (PMID 34201504, 2021). "For instance, B-cell eCGIs are enriched for regions binding key TFs involved in B-lymphopoiesis and lymphoma pathogenesis (such as BCL11A, EBF1, IKZF1 and SPI1), whereas ESC-specific eCGIs are enriched for binding of NANOG, a key TF regulating pluripotency." (PMID 26512062, 2016). "There are currently no reported studies investigating the relationship between SPI1 gene expression and resistance to ICT in melanoma., but this gene is downregulated and methylated in more than 70% of lymphoma patients." (PMID 37077920, 2023).
erythroleukemia (22 papers, 2008 to 2025). Acute erythroid leukemia characterised by the presence of at least 50% erythroid precursors and at least 20% myeloblasts in the bone marrow. "Over‐expression of SPI1 is known to cause erythro leukemia by inhibiting apoptosis and blocking the terminal differentiation of erythrocytes." (PMID 27506447, 2016). "Diseases associated with SPI1 include inflammatory diarrhea and erythroleukemia." (PMID 35065610, 2022). "Indeed, most of these clonal erythroleukemia are associated with one of three recurrent proviral insertions leading to spi-1, fli-1 or fli-3 genes deregulated expression." (PMID 23056458, 2012). "Moreover, the Spi-1 proto-oncogene (SPI1), which encodes PU.1 (a member of the E26-transformation-specific transcription factor family), has been found to function as an oncogene specifically activated in acute murine erythroleukemias induced by the Friend spleen focus-forming virus (SFFV)." (PMID 39062086, 2024). "Spi‐1 proto‐oncogene (SPI1) is an oncogene specifically activated in acute murine erythroleukemias induced by the Friend spleen focus forming virus (SFFV), which is located in the p11.22 region of human chromosomes." (PMID 37539493, 2023). "In the present research, SPI1 was identified as a supposed oncogene in virus‐induced murine erythroleukemias." (PMID 37539493, 2023). "In erythroleukemia, the transcription factor Spi-1/PU.1 inhibits apoptosis through transcriptional repression of Bim." (PMID 26405162, 2015). "Additionally, in a Spi-1/Pu.1 transgenic mouse model where mice develop erythroleukemia, it has also been shown that Bim levels are downregulated through Pu.1 activity, as Pu.1 binds the Bim promoter and promotes repressive H3K27 trimethylation." (PMID 35538058, 2022). "Such highly recurrent activation of one of these two transcription factors belonging to the same ETS family led us to hypothesize that Spi-1 and Fli-1 could contribute to erythroleukemia through common target genes deregulation." (PMID 23056458, 2012). "In murine erythroleukemia, HDAC1 cooperates with SPI-1 proto-oncogene (SPI1)-induced transcriptional repression by deacetylating SPI1-bound enhancers of genes involved in erythroid differentiation." (PMID 40603833, 2025). "In a model of erythroleukemia induced by overexpression of SPI1/PU.1 in proerythroblasts, as well as in Spi-1 overexpressing transgenic mice, Sphk1 was found to be transcriptionally upregulated." (PMID 36361536, 2022). "In contrast, SPI1 has been reported to exert an oncogenic role in non-small cell lung carcinoma (NSCLC) and virally induced murine erythroleukemia." (PMID 36509766, 2022).
acute promyelocytic leukemia (18 papers, 2009 to 2025). An aggressive form of acute myeloid leukemia (AML), characterized by arrest of leukocyte differentiation at the promyelocyte stage, due to a specific chromosomal translocation t(15;17) in myeloid cells. "Our group previously identified HK3 as a transcriptional target of the hematopoietic transcription factor PU.1 (SPI1) during acute promyelocytic leukemia (APL) differentiation." (PMID 35538058, 2022).